FLII (FLII actin remodeling protein)
Description:
Is a regulator of actin polymerization, required for proper myofibril organization and regulation of the length of sarcomeric thin filaments (By similarity). It also plays a role in the assembly of cardiomyocyte cell adhesion complexes (By similarity). Regulates cytoskeletal rearrangements involved in cytokinesis and cell migration, by inhibiting Rac1-dependent paxillin phosphorylation (By similarity). May play a role as coactivator in transcriptional activation by hormone-activated nuclear receptors (NR) and acts in cooperation with NCOA2 and CARM1. Involved in estrogen hormone signaling.
Synonyms: FLIL; FLI; Fli1; MGC39265; CMD2J
Tractability: PROTAC: ubiquitination databases record sites on it; its protein half-life has been measured.
Gene: Protein-coding gene on chromosome 17 (18,244,782 to 18,258,772, reverse strand). Ensembl gene ENSG00000177731.
Subcellular location: Nucleus; Cytoplasm, cytoskeleton; Cytoplasm, cytoskeleton, microtubule organizing center, centrosome; Cell projection, podosome; Cell junction, focal adhesion
Subcellular location (Human Protein Atlas): Centriolar satellite; Cytosol; Nucleoplasm
Gene Ontology:
Molecular function: actin binding; protein binding; phosphatidylinositol-4,5-bisphosphate binding; actin filament binding
Biological process: actin filament severing; actin polymerization or depolymerization; barbed-end actin filament capping; myofibril assembly; sarcomere organization
Cellular component: nucleus; podosome; brush border; centrosome; cytoskeleton; focal adhesion
Genetic constraint (gnomAD): Loss-of-function variants: 101 observed, 159.07 expected, observed/expected ratio (o/e) 0.63, 90% interval 0.54 to 0.75. The upper end of that interval is the gene's LOEUF score, 0.75, which puts it in group 3 of 6, group 1 being the genes least tolerant of losing a copy. Missense variants: 1,675 observed, 1,711.9 expected, observed/expected ratio (o/e) 0.98, 90% interval 0.94 to 1.02. Synonymous variants: 767 observed, 700.98 expected, observed/expected ratio (o/e) 1.09, 90% interval 1.03 to 1.16.
Gene-disease validity (ClinGen):
ClinGen rates the evidence that FLII causes each of these diseases.
cardiomyopathy, dilated, 2j (autosomal recessive): Moderate.
Homologues: Orthologues: macaque FLII (99% identical), chimpanzee FLII (98% identical), mouse Flii (95% identical), rat Flii (95% identical), pig FLII (95% identical), guinea pig FLII (95% identical), dog FLII (88% identical), tropical clawed frog flii (84% identical), zebrafish flii (83% identical), Drosophila melanogaster fliI (56% identical), rabbit FLII (54% identical), Caenorhabditis elegans fli-1 (50% identical). Paralogues in human: SVIL (19% identical), AVIL (18% identical), VIL1 (18% identical), SCIN (18% identical), GSN (17% identical), VILL (15% identical), CAPG (8% identical).
Diseases named in the same sentence as FLII in open-access papers:
FLII is named in the same sentence as 25 diseases in open-access papers, as found by Europe PMC text mining. Sharing a sentence is not in itself a finding about the gene and the disease. The quoted sentences say what the papers report.
breast carcinoma (2 papers, 2021 to 2025). "FLII homolog inhibits androgen receptor signaling, slowing prostate cancer development, while FLII itself inhibits selective autophagy and promotes breast cancer growth by blocking p62‐mediated recognition of LC3." (PMID 39964147, 2025). "FLII has been recently reported to promote breast cancer progression via inhibiting p62-mediated selective autophagy and block apoptosis in colon cancer cells by regulating Ca2+ homeostasis." (PMID 34571936, 2021).
colon cancer (2 papers, 2020 to 2021). "In this study, we demonstrate that Flightless-1 (FliI) regulates ER stress-induced apoptosis in colon cancer cells by modulating Ca2+ homeostasis." (PMID 32504039, 2020). "Here, we report a novel function of FliI: FliI suppresses ER stress-induced UPR signaling and apoptosis in colon cancer by regulating Ca2+ homeostasis through modulation of RyR activity." (PMID 32504039, 2020).
glioblastoma (2 papers, 2021 to 2026). The most malignant astrocytic tumor (WHO grade IV). "Clinical samples further confirmed the co-upregulation of NIBAN2, FLII, and RREB1 in GBM (Glioblastoma) tissues, which correlates with SOX2 and Ki-67 expression and poor prognosis." (PMID 41736673, 2026).
prostate carcinoma (2 papers, 2023 to 2024). A carcinoma that arises from epithelial cells of the prostate gland. "Both in silico and in human prostate cancer immunostaining, the expression of FliI was positively correlated with the overall survival of prostate cancer patients." (PMID 39000020, 2024). "Also, FLII plays a tumor-suppressive role and is considered a critical determinant of prostate cancer resistance to endocrine-based therapies." (PMID 37762638, 2023).
cardiomyopathy (1 paper, 2024). A disease of the heart muscle or myocardium proper. "Recently, the human pathogenic p.R1243H mutation in the FLII (Flightless-I homolog) gene, predisposing to cardiomyopathy, was investigated in a series of mouse models." (PMID 38168645, 2024).
colitis (1 paper, 2020). Inflammation of the colon. "To investigate the clinical relevance of FliI in CRC, we first examined FliI expression in both CRC cell lines and cancer tissue in the APCmin+- and colitis-induced mouse model of CRC." (PMID 32504039, 2020).
colorectal cancer (1 paper, 2020). A primary or metastatic malignant neoplasm that affects the colon or rectum. "In a mouse xenograft model using CT26 mouse colorectal cancer cells, tumor formation was slowed due to elevated levels of apoptosis in FliI-knockdown (FliI-KD) cells." (PMID 32504039, 2020). "FliI was highly expressed in both colon cell lines and colorectal cancer mouse models." (PMID 32504039, 2020).
cutaneous abscesses (1 paper, 2017). "A PA14 strain with a mutation in the gene encoding the global regulator AlgR, like the flagellin FliI mutant, caused cutaneous abscesses and dermonecrosis similar to those seen with strain LESB58 but no lethality." (PMID 28246361, 2017).
endometrial cancer (1 paper, 2025). Primary or metastatic malignant neoplasm involving the endometrium (mucous membrane that lines the endometrial cavity). "The low expression of CAPG, AVIL, and SVIL, together with the high expression of GSN, VILL, and FLII, were found to be significantly associated with poor overall survival in endometrial cancer patients." (PMID 39964147, 2025). "In vitro studies showed that silencing CAPG and FLII could inhibit proliferation and metastasis in endometrial cancer cell lines." (PMID 39964147, 2025).
tumor (11 papers, 1999 to 2025). "Consequently, clinicopathological characteristics and the expression levels of GSN, SCIN, CAPG, VILL, VIL1, SVIL, and FLII were found to be closely associated with tumor stages in EC." (PMID 39964147, 2025). "Many studies have supported the idea that FliI plays important roles in tumor progression by stimulating cell proliferation, inhibiting apoptosis, and promoting invasion." (PMID 32504039, 2020). "The STS also suppressed the FliI, an actin remodelling protein that enhances tumour progression by decreasing apoptosis and inducing cell invasion." (PMID 32533048, 2020). "Downregulation of Flightless I homolog (FLII) during resistance leads to activation of the YBX1/PD-L1 axis, generating an immunosuppressive tumor microenvironment." (PMID 41346602, 2025). "Furthermore, FliI modulates cell proliferation and survival in cancer cells by interacting with transcription factors such as androgen receptor, estrogen receptor (ER), and carbohydrate responsive element-binding protein, which regulate tumor progression in prostate cancer and CRC cells." (PMID 32504039, 2020). "In this core signaling pathway, the transduction signaling protein FLII plays a role in regulating cytoskeletal rearrangement involved in cell division and cell metastasis; E2F4 plays an important role in controlling the cell cycle and inhibiting tumor proteins." (PMID 35743172, 2022).
infection (9 papers, 2013 to 2024). The state of being infected such as from the introduction of a foreign agent such as serum, vaccine, antigenic substance or organism. "C57BL/6 macrophages triggered robust pore formation in response to infection with fliI- and reduced pore formation in response to flaA-." (PMID 28771586, 2017). "This suggests that FliI can be used for immunomodulation and infection in the host." (PMID 37953796, 2023). "Since we assumed that dissemination of Pseudomonas from the infection site might be a limitation in establishing a chronic infection, we tested a fliI mutant of strain PA14." (PMID 28246361, 2017). "We found that infection with wild type bacteria and fliI mutants (that express cytosolic flagellin, but do not assembly the flagellum), but not with flaA mutants, triggers robust CASP8 activation in Casp1/11–/–and Gsdmd–/–macrophages." (PMID 31251782, 2019). "We found that ASC puncta formed readily after the infection and that this process occurred in response to WT Lp and fliI- but not flaA-." (PMID 28771586, 2017). "In contrast, pore formation was evident in Casp1/11-/- but not in Asc/Casp1/11-/- macrophages in response to fliI- infection." (PMID 28771586, 2017). "Cell death was flagellin-dependent because infections with fliI- but not flaA- induced LDH release." (PMID 28771586, 2017). "Moreover, during in vivo co-cultures, transcriptomic analysis revealed an upregulation of transposases, flagellum-related genes (fliI and flgK), transporters, and permeases that could unveil novel virulence effectors used in the early infection process of P. salmonis." (PMID 37953796, 2023).
cancer (2 papers, 2020 to 2022). A tumor composed of atypical neoplastic, often pleomorphic cells that invade other tissues. "Therefore, targeting FliI represents an innovative and effective strategy for the development of cancer therapeutics." (PMID 32504039, 2020). "Suppressing FliI activity could thus help sensitize cancer cells to other stress- and death-inducing drug regimens." (PMID 32504039, 2020). "FliI expression in CRC cell lines and cancer tissues was significantly higher than that in the corresponding normal cell line and nontumor tissues." (PMID 32504039, 2020). "GEPIA2 database analysis of 33 cancer types showed the following top 10 ALKBH5-related genes: GID4 (R=0.71), TOP3A (R=0.67), MAPK7 (R=0.66), NT5M (R=0.61), FLII (R=0.59), ZNF18 (R=0.57), DRG2 (R=0.57), COPS3 (R=0.56), MED9 (R=0.56) and PRPSAP2 (R=0.56) (all P<0.0001)." (PMID 35444654, 2022).
cardiac disease (1 paper, 2023). "However, the precise role of FLII in cardiomyocytes remains poorly understood, and there is scarce evidence regarding the potential association between FLII variants and human cardiac disease." (PMID 37561591, 2023).
FLII also shares sentences with these, for which no sentence is quoted: cardiovascular diseases (1 paper); diffuse large B-cell lymphoma (1); fibrosis (1); glioma (1); Hepatic fibrosis (1); myeloid leukemia (1); nutritional deficiency (1); renal carcinoma (1); Salmonella Infections (1); sarcoma (1); Smith-Magenis syndrome (1); viral infection (1).